NRAS (NRAS proto-oncogene, GTPase)
Diseases named in the same sentence as NRAS in open-access papers (continued):
Sharing a sentence is not in itself a finding about the gene and the disease.
melanoma (continued). "Another study identified acquired NRAS and PIK3CA mutations in cfDNA samples obtained from melanoma patients who had progressed on BRAF/MEKi." (PMID 39859576, 2025). "Genetic mutations in KRAS, NRAS, and BRAF were commonly implicated in the development of both melanoma and CRC, while mutations in CDKN2A and BRCA2 were specifically significant in melanoma." (PMID 40447784, 2025). "Our findings establish that NRAS can be broadly, directly, and efficiently targeted with ASOs in NRAS-mutant melanoma, potentially opening new therapeutic avenues for melanoma patients." (PMID 40473796, 2025). "Mechanistically, we show that ATAD2 inhibition activates both distinct and common tumor-suppressive pathways in BRAF and NRAS mutant melanoma." (PMID 41331524, 2025). "NRAS-mutant melanoma represents a clinically challenging subset of melanoma with limited effective therapies and intrinsic resistance to targeted MEK inhibition." (PMID 40563669, 2025). "In a recent study a researcher performed single-cell RNA sequencing on NRAS-mutant melanomas treated with MEK1/2 and CDK4/6 inhibitors to decode the transcriptional transitions occurring during the development of drug resistance." (PMID 40872623, 2025). "In contrast, a strong dependency on NRAS-mRNA expression was observed in 81.8% of NRAS-mutant melanoma cell lines (9 of 11) in the CRISPR group and in 66.7% of NRAS-mutant melanoma cell lines (4 of 6) in the RNAi group." (PMID 40473796, 2025). "The let‐7 family of miRNAs is frequently downregulated in melanoma, where it targets multiple oncogenes, including NRAS and MYC." (PMID 39823244, 2025). "This combination demonstrates superior efficacy in preclinical models, suggesting that NOS inhibition can sensitize NRAS-mutant melanoma cells to targeted therapy." (PMID 40563669, 2025). "While KRAS mutations in cutaneous melanoma occur less frequently than BRAF or NRAS mutations, KRAS-linked signaling has garnered attention in other malignancies and exhibits the potential to influence melanoma cell proliferation and phenotypic plasticity." (PMID 40607411, 2025). "Aside from the differences in testing methods and sensitivity levels, a literature review demonstrates that NRAS and BRAF mutations are mutually exclusive in melanoma." (PMID 39940799, 2025). "Approximately 85% of melanomas harbor primary pathogenic alterations in key genes such as BRAF, NRAS, NF1 or KIT, which include mutations, deletions or amplifications." (PMID 39859576, 2025). "Genetically, male melanoma patients exhibit higher mutation rates in BRAF and NRAS, along with lower expression of ERβ, while elderly patients tend to have increased NRAS mutations and decreased BRAF mutations." (PMID 41085102, 2025). "KIT mutations tend to occur in acral, mucosal, and CSD melanomas in older patients, and are often mutually exclusive of BRAF and NRAS mutations." (PMID 41301010, 2025). "In one study, 161 stage II–III high-risk resected melanoma patients treated with adjuvant bevacizumab versus (vs.)placebo within the AVAST-M clinical trial were studied with ddPCR to detect BRAF and NRAS common mutations in plasma." (PMID 39859576, 2025). "Genetic mutation, especially in the BRAF, NRAS, and CDKN2A genes, plays a very significant part in the development of melanoma." (PMID 41049012, 2025).
melanoma (continued). "In melanoma, mutations in BRAF V600 (present in 40–60% of patients) or NRAS Q61 (found in about 25%) make these methods particularly effective for analyzing ctDNA in most cases." (PMID 39859576, 2025). "In this experimental setting, the STK19 p.Asp89Asn mutation behaved as gain-of-function missense substitution that enhances NRAS phosphorylation, melanocyte transformation, and NRAS-driven melanoma development in mice." (PMID 41278537, 2025). "Most patients with CLL and melanoma are diagnosed with pathologic Stage III disease or lower, and a literature review has demonstrated that melanoma in patients with CLL has variable incidences of BRAF and NRAS mutations." (PMID 39940799, 2025). "In melanomas, Class I MAP2K1 mutations have been identified as secondary oncogenic drivers, typically occurring alongside BRAF, NRAS, or NF1 mutations." (PMID 40107205, 2025). "NRAS mutant melanomas are also characterized by the activation of several signaling pathways (PI3K/AKT, RAL-GEF and cell cycle regulators) in addition to the MAPK pathway, in contrast to BRAF mutants." (PMID 40361349, 2025). "Melanomas, while typically benign in cutaneous forms, exhibit aggressive behavior in oral and digital locations, with BRAF and NRAS mutations playing an integral role in tumor growth." (PMID 41394861, 2025). "Conversely to WT melanomas, those harboring a mutation in BRAF, NRAS, or cell cycle reported clinical and dermoscopic features underlying a more aggressive phenotype." (PMID 40867317, 2025). "For NRAS-mutated melanoma, due to the limited efficacy of MEKis, first-line immunotherapy options are identical to those for NRAS-WT melanoma." (PMID 39550033, 2025). "In summary, the therapeutic modulation of protein S-nitrosylation offers a compelling new avenue to overcome resistance and reinvigorate anti-tumor immunity in NRAS-mutant melanoma, warranting further preclinical and clinical investigation." (PMID 40563669, 2025). "Molecular profiling confirmed the diagnosis of melanoma and identified mutations in the TERT promoter, NRAS, NF1, PBRM1, FAT1, and ATM genes." (PMID 40125165, 2025). "Although BRAF mutant melanoma has attracted much attention, NRAS was actually the first melanoma oncogene to be identified." (PMID 41160271, 2025). "Their findings demonstrate that the ASOs effectively eliminate NRAS-dependent melanoma cells, inhibit MAPK signaling, and synergize with kinase inhibitors, offering a promising strategy for clinical applications." (PMID 40473796, 2025). "NRAS-mutant melanomas demonstrate aggressive clinical behavior and pose significant therapeutic challenges, as effective targeted therapies remain elusive compared to their BRAF-mutant counterparts." (PMID 40563669, 2025). "The genes most frequently associated with melanoma pathogenesis include BRAF, NRAS, neurofibromin 1 (NF1), and KIT." (PMID 39859576, 2025). "Melanotic melanoma cells often retain functional melanogenesis pathways and carry mutations commonly found in cutaneous melanoma, such as BRAF V600E, NRAS or NF1." (PMID 40649764, 2025). "Understanding how S-nitrosylation governs immune surrender will be essential for designing combinatorial therapies that overcome resistance in aggressive NRAS-mutant melanomas." (PMID 40563669, 2025). "The activation of the MAPK and PI3K pathways is nearly universal in melanoma tumors principally due to mutually exclusive mutations in BRAF (40–50% of cases) or NRAS (15–20%) or to the losses of NF1 expression (13%) that may co-occur with BRAF or NRAS mutations." (PMID 40282469, 2025). "NRAS mutations, particularly NRAS Q61K/R, are a commonly observed acquired resistance mechanism in patients with BRAF-mutant melanoma treated with BRAF+/−MEK inhibitors." (PMID 39859576, 2025). "A similar phenomenon is observed in BRAF-mutant melanoma, where co-occurring PTEN loss or NRAS mutations activate alternative signaling pathways, ultimately limiting the efficacy of BRAF inhibitors." (PMID 40076838, 2025).
melanoma (continued). "For instance, mutations in the BRAF, NRAS, and KIT genes are well-documented in human melanomas, leading to constitutive activation of the MAPK pathways promoting tumorigenesis." (PMID 41394861, 2025). "The molecular development of melanoma is mainly associated with mutations in the v-Raf (BRAF), NF-1 (neurofibromin 1), NRAS (neuroblastoma RAS viral oncogene homolog), and MC1R (melanocortin 1 receptor) genes." (PMID 40710294, 2025). "In contrast, there are limited treatment choices for patients with NRAS-mutant or BRAFWT/NRASWT melanoma who progress after ICI therapy (i.e., de novo or acquired resistance)." (PMID 40904502, 2025). "Although the administration of αPD-1 alone reduced the growth of YUMM5.2 allograft melanoma lesions, this treatment had only a marginal impact on NRAS;Ink4a tumors." (PMID 40530504, 2025). "For that, we expressed PAGFP-RBD (of BRAF) and PAmCherry-NRas in 108T melanoma cells, imaged them, and analyzed their mutual organization using the same approach." (PMID 41373795, 2025). "The genomic landscape of melanoma features numerous genomic alterations with key driver mutations in genes, such as BRAF (45%), NRAS (17%), and KIT (9%), leading to dysregulated cell growth and survival pathways." (PMID 40004220, 2025). "Melanoma is classically driven by mutations in genes such as BRAF, NRAS, and c-KIT, which promote uncontrolled cell growth and survival." (PMID 40725203, 2025). "Although trametinib is known to be highly effective against BRAF/NRAS wild-type melanoma, its sensitivity in NF1-negative melanoma cell lines is comparable to that in NF1-expressing lines, suggesting that further research is required." (PMID 41001300, 2025). "Genetic mutations in KRAS, NRAS, and BRAF were frequently observed in both melanoma and CRC, whereas BRCA2 and CDKN2A mutations were specific to melanoma." (PMID 40447784, 2025). "This underscores the therapeutic promise of targeting HSP70, as supported by previous findings showing synergy between HSP70 and MEK inhibitors in NRAS-mutant melanoma." (PMID 41148289, 2025). "There is also a “rule of thumb” in melanoma, i.e., only one oncogene can be mutated in the same pathway, meaning that these three mutations (KIT/NRAS/BRAF) are mutually exclusive." (PMID 40361349, 2025). "Targeting the MAP2K kinases in NRAS-mutant melanoma represents a well-established approach in targeted therapy." (PMID 40473796, 2025). "The aims of the study were to assess the clinical, histopathological, and dermoscopic features of melanoma to identify their correlation with BRAF, NRAS, and cell cycle genes’ mutational status in melanoma." (PMID 40867317, 2025). "Tunlametinib, another MEK inhibitor, resulted in significant antitumor activity in patients with inoperable, stage III/4 NRAS-mutant melanomas with prior exposure to immunotherapy." (PMID 41516092, 2025). "In contrast, NRAS-mutant melanoma poses unique therapeutic challenges and is characterized by resistance to existing targeted therapies and aggressive tumor growth." (PMID 40473796, 2025). "Drugs that target MAPK-pathway signaling offer limited clinical benefit for NRAS-mutant melanoma patients due to early onset treatment resistance." (PMID 40473796, 2025). "The MAPK pathway has a crucial role in melanoma pathogenesis and is activated by mutations in the key signalling pathway members, including BRAF, NRAS, NF1 and KIT." (PMID 41017066, 2025). "Mutation of BRAF and NRAS and overexpression of PGC-1α in melanoma cells indicate high OXPHOS and a greater dependency of these cells on glycolysis." (PMID 40404919, 2025). "In NRAS-mutant melanoma, S-nitrosylation contributes to MEK-ERK pathway hyperactivation and resistance to MEK inhibitors." (PMID 40563669, 2025). "Mechanistic investigations have revealed that the novel Pyrrolidine Diketopiperazines 2155-14 and 2155-18 induce ER stress, which enhances basal autophagy and ultimately leads to melanoma cell death in BRAF- and NRAS-mutated melanoma cells." (PMID 40331942, 2025).
melanoma (continued). "Recent large-scale genomic studies in melanoma have primarily focused on mutation profiles predictive of response to treatments such as BRAF, NRAS, and CKIT inhibitors." (PMID 40004220, 2025). "Metabolism reprogramming induced by 2DG makes the neuroblastoma RAS viral oncogene homolog (NRAS) mutant melanoma cells sensitive to BRAF inhibitor (BRAFi) sorafenib." (PMID 40617808, 2025). "The melanoma cells in this study were derived from human NRAS-mutant tumors, which are difficult to treat with targeted kinase inhibitors compared to BRAF-mutant tumors." (PMID 39996721, 2025). "Targeting nodes of the AKT and MAPK survival pathways with trametinib and capivasertib highlights the potential for combination therapies for NRAS-mutant melanoma stem cells for the development of more effective treatments for patients with high-risk melanoma." (PMID 39996721, 2025). "Kinome activity profiling of NRAS ASO-1 treated melanoma cells revealed MEK1 as the most significantly upregulated kinase in response to NRAS ASO treatment, which was therapeutically exploitable." (PMID 40473796, 2025). "Our research extends previous efforts that used siRNAs to mainly explore the role of NRAS in melanoma related signal transduction and cell cycle regulation." (PMID 40473796, 2025). "Experiments evaluating the effect of SX-682, palbociclib, or the combination of inhibitors were also conducted in C57Bl/6 mice bearing 1014 NRAS mutant (NRASmut) melanoma xenografts over a treatment period of two weeks." (PMID 40904502, 2025). "Immunogenicity is inferred by the fact that homologous NRAS mutations (ILDTAGKEEY, ILDTAGREEY) have been shown to be immunogenic in HLA-A*01:01-positive melanoma patients and presentation of the peptides was shown by immunopeptidomics." (PMID 40165973, 2025). "Genetic or pharmacological inhibition of ATAD2 suppresses the growth and metastasis of BRAF and NRAS mutant melanoma." (PMID 41331524, 2025). "Melanoma is primarily driven by mutations in proteins of the MAPK pathway, such as BRAF, NRAS, NF1, or the RTK cKIT." (PMID 40943167, 2025). "The proline 29 to serine (P29S) mutation in RAC1 is the third most common hotspot mutation in melanoma, following BRAF V600E and neuroblastoma RAS viral oncogene homolog (NRAS) Q61R." (PMID 41034404, 2025). "PLX4720-mediated apoptosis resistance via upregulated Mcl-1 was accompanied by highly invasive properties in NRAS-mutant melanoma cells." (PMID 39935431, 2025). "Melanoma CSCs often harbor mutations in such genes as BRAF and NRAS, which are associated with resistance mechanisms, including the reactivation of mitogen-activated protein kinases (MAPK) signaling pathways." (PMID 40867277, 2025). "Efforts to elucidate the molecular hallmarks of melanoma have long focused on canonical mutations in genes such as BRAF and NRAS." (PMID 40607411, 2025). "In BRAF- and NRAS-mutant melanoma patients, low ACKR2 expression or high CCL5/CXCL10 levels correlated with improved survival and higher CD8+ T cell markers." (PMID 40248897, 2025). "Similar to findings in White melanoma studies, variants in BRAF (25%), NRAS (20%), NF1 (17%), and KIT (17%) were prevalent in Japanese melanomas (Appendix Fig A1B)." (PMID 39823560, 2025). "NRAS-driven melanomas are characterized by unique clinical features, such as thicker tumors, higher rates of occurrence on extremities, rapid onset of treatment resistance, and higher mitotic indices." (PMID 40473796, 2025). "Currently, immunotherapy with anti-PD-1 checkpoint inhibitors stands as the primary pharmacological treatment for NRAS-mutant melanoma, albeit offering patients only modest benefits." (PMID 40473796, 2025).
melanoma (continued). "Our study revealed that in NRAS-mutant melanoma cells, ERK remains persistently activated despite MEK inhibition, a phenomenon driven by S-nitrosylation." (PMID 40563669, 2025). "Mutations in the NRAS GTPase are the second most common mutation noted in melanoma after BRAF, observed in 15–20% of melanomas." (PMID 39859464, 2025). "Most were gain-of-function mutations (e.g., E545K, H1047R), which are known to confer resistance to MEK and CDK4/6 inhibitors in NRAS-mutant melanoma." (PMID 40652269, 2025). "Despite these advances, the ideal treatment for NRAS-mutant melanoma remains elusive, necessitating further research." (PMID 40508177, 2025). "Evidence has also shown that the microenvironment in NRAS-mutant melanoma BMs is enriched in neutrophils in contrast to the primary melanoma." (PMID 40076927, 2025). "The KIT/NRAS/BRAF signaling pathway is the dominant pathway in both melanocytes and melanomas, which is why mutations in these oncogenes occur with such frequency." (PMID 40361349, 2025). "NRAS mutations are present in approximately 20% of human melanomas, whereas HRAS and KRAS mutations occur in only 1% and 2% of melanomas, respectively." (PMID 40076927, 2025). "All these findings highlight that mdivi-1-mediated inhibition of mitochondrial fission sensitizes NRAS-mutant melanoma cells to the antitumor effects of vemurafenib." (PMID 40141318, 2025). "Both RAS-mediated downstream effector pathways share closely interconnected regulatory mechanisms, ultimately contributing to the cellular survival of NRAS-mutant melanoma cells." (PMID 40473796, 2025). "We tested the impact of NRAS ASO-1 treatment on cell proliferation in nine NRAS-mutant melanoma cell lines, including the primary derived cell line Hs852T." (PMID 40473796, 2025). "Treatment with 10 μM 2-BP for 2 h in WM3000 melanoma cells caused a reduction in the expression level of palmitoylated NRAS, while 20 μM 2-BP treatment for 3 min in HeLa S2 cells expressing EGFP-NRAS caused it to delocalize from the plasma membrane." (PMID 40004137, 2025). "(0 of 55 NRAS-WT melanoma cell lines in the CRISPR-group and 0 of 38 NRAS-WT melanoma cell lines in the RNAi-group)." (PMID 40473796, 2025). "All in all, NRAS mutant melanoma presents unique challenges in treatment and prognosis, prompting a need for novel and more effective therapies." (PMID 40867277, 2025). "In conclusion, our results together show that capivasertib works synergistically with trametinib to inhibit the growth of drug-resistant NRAS-mutant melanoma CSCs, both in vitro and in vivo." (PMID 39996721, 2025). "We have demonstrated that the RAC1-GEF PREX1 plays critical roles in melanoblast migration during early murine embryonic development, melanoma cell invasion and migration, and metastasis in a patient-relevant preclinical model of NRAS-mutant melanoma." (PMID 39636745, 2025). "Our approach demonstrates that NRAS-mutant melanoma cells can be specifically targeted by exploiting the full sequence, allowing to target various NRAS-mutant melanoma subtypes with the same ASO sequence." (PMID 40473796, 2025). "Protein S-nitrosylation emerges as a dynamic and reversible post-translational modification that critically regulates both oncogenic signaling and immune modulation in NRAS-mutant melanoma." (PMID 40563669, 2025). "In contrast, DNA damage, DNA repair and cell cycle signatures showed significant enrichment in NRAS wild‐type melanoma." (PMID 39757723, 2025).